MBTPS1 (membrane bound transcription factor peptidase, site 1)
Description:
Serine protease that cleaves after hydrophobic or small residues, provided that Arg or Lys is in position P4: known substrates include SREBF1/SREBP1, SREBF2/SREBP2, BDNF, GNPTAB, ATF6, ATF6B and FAM20C. Cleaves substrates after Arg-Ser-Val-Leu (SREBP2), Arg-His-Leu-Leu (ATF6), Arg-Gly-Leu-Thr (BDNF) and its own propeptide after Arg-Arg-Leu-Leu. Catalyzes the first step in the proteolytic activation of the sterol regulatory element-binding proteins (SREBPs) SREBF1/SREBP1 and SREBF2/SREBP2. Also mediates the first step in the proteolytic activation of the cyclic AMP-dependent transcription factor ATF-6 (ATF6 and ATF6B). Mediates the protein cleavage of GNPTAB into subunit alpha and beta, thereby participating in biogenesis of lysosomes. Cleaves the propeptide from FAM20C which is required for FAM20C secretion from the Golgi apparatus membrane and for enhancement of FAM20C kinase activity, promoting osteoblast differentiation and biomineralization. Involved in the regulation of M6P-dependent Golgi-to-lysosome trafficking of lysosomal enzymes. It is required for the activation of CREB3L2/BBF2H7, a transcriptional activator of MIA3/TANGO and other genes controlling mega vesicle formation. Therefore, it plays a key role in the regulation of mega vesicle-mediated collagen trafficking. Promotes FAD binding to the ETFA/ETFB complex and is therefore involved in mitochondrial respiratory chain regulation. In astrocytes and osteoblasts, upon DNA damage and ER stress, mediates the first step of the regulated intramembrane proteolytic activation of the transcription factor CREB3L1, leading to the inhibition of cell-cycle progression.
Synonyms: SKI-1; KIAA0091; S1P; PCSK8; CAOP; SEDKF
Tractability: Small molecule: a high-quality ligand is known; it belongs to a druggable protein family. Antibody: UniProt predicts a signal peptide or a membrane-spanning region. PROTAC: ubiquitination databases record sites on it; a small molecule that binds it is known.
Target class: Enzyme; Serine protease SB clan; Protease; Serine protease; Serine protease S8A subfamily
Gene: Protein-coding gene on chromosome 16 (84,053,761 to 84,116,942, reverse strand). Ensembl gene ENSG00000140943.
Subcellular location: Endoplasmic reticulum membrane; Golgi apparatus membrane; Secreted; Mitochondrion
Pathways (Reactome):
Cellular responses to stimuli: ATF6 (ATF6-alpha) activates chaperones; ATF6B (ATF6-beta) activates chaperones; CREB3 factors activate genes
Metabolism of proteins: Post-translational protein phosphorylation; Regulation of Insulin-like Growth Factor (IGF) transport and uptake by Insulin-like Growth Factor Binding Proteins (IGFBPs)
Metabolism: Regulation of cholesterol biosynthesis by SREBP (SREBF)
Transport of small molecules: Assembly of active LPL and LIPC lipase complexes
Gene Ontology:
Molecular function: protein binding; serine-type endopeptidase activity; endopeptidase activity; serine-type peptidase activity
Biological process: lysosome organization; protein maturation; protein processing; proteolysis; regulation of vesicle-mediated transport; ATF6-mediated unfolded protein response; endoplasmic reticulum unfolded protein response; membrane protein intracellular domain proteolysis; regulation of cholesterol biosynthetic process; response to endoplasmic reticulum stress; mitotic G2 DNA damage checkpoint signaling
Cellular component: endoplasmic reticulum membrane; extracellular region; Golgi membrane; mitochondrion; endoplasmic reticulum lumen; Golgi stack
Genetic constraint (gnomAD): Loss-of-function variants: 78 observed, 110.66 expected, observed/expected ratio (o/e) 0.7, 90% interval 0.59 to 0.85. The synonymous counts are far from expectation, so gnomAD's model fits this gene poorly and the ratio says little. Missense variants: 1,504 observed, 1,295.2 expected, observed/expected ratio (o/e) 1.16, 90% interval 1.11 to 1.21. Synonymous variants: 598 observed, 492.42 expected, observed/expected ratio (o/e) 1.21, 90% interval 1.13 to 1.3.
Gene-disease validity (ClinGen):
ClinGen rates the evidence that MBTPS1 causes each of these diseases.
spondyloepiphyseal dysplasia, kondo-fu type (autosomal recessive): Definitive. A disorder characterized by severely retarded growth, spondyloepiphyseal dysplasia, reduced bone mineral density, and markedly elevated plasma levels of various lysosomal enzymes.
Homologues: Orthologues: chimpanzee MBTPS1 (99% identical), guinea pig MBTPS1 (98% identical), dog MBTPS1 (97% identical), macaque MBTPS1 (97% identical), rat Mbtps1 (97% identical), pig MBTPS1 (97% identical), mouse Mbtps1 (96% identical), rabbit MBTPS1 (96% identical), zebrafish mbtps1 (84% identical), tropical clawed frog mbtps1 (79% identical), Drosophila melanogaster S1P (45% identical). Paralogues in human: PCSK5 (18% identical), PCSK6 (15% identical), FURIN (15% identical), PCSK4 (13% identical), PCSK7 (13% identical), PCSK1 (12% identical), PCSK2 (11% identical), TPP2 (10% identical), PCSK9 (8% identical).
Diseases named in the same sentence as MBTPS1 in open-access papers:
MBTPS1 is named in the same sentence as 358 diseases in open-access papers, as found by Europe PMC text mining. Sharing a sentence is not in itself a finding about the gene and the disease. The quoted sentences say what the papers report.
breast carcinoma (52 papers, 2012 to 2025). "Previous studies showed that the decreased expression of MBTPS1 produced by chromosome 16q loss were reported in the oestrogen receptor (ER)-positive breast cancer." (PMID 36304471, 2022).
atherosclerosis (37 papers, 2011 to 2025). A disease characterized by the build-up of fatty material and calcium deposition in the arterial wall resulting in partial or complete occlusion of the arterial lumen. "In atherosclerosis, we found that the expression of FURIN, PCSK5 and MBTPS1 was significantly lower in carotid plaques vs. normal artery controls, while PCSK6 and PCSK7 were increased." (PMID 36188622, 2022).
diabetes (32 papers, 2009 to 2025). "Lindenmeyer and colleagues demonstrated that mRNA expression of GRP78/BiP, ORP150/HYOU1, S1P (MBTPS1), calnexin and XBP-1 increase in the kidneys of patients with established diabetes, compared with mild diabetes." (PMID 26239352, 2015).
colon cancer (29 papers, 2015 to 2025). "Based on the knockdown of MBTPS1, the inhibition of the type 1 interferon pathway completely inhibits tumor proliferation, which suggests that MBTPS1 can be used as a therapeutic target for the treatment of colon cancer." (PMID 37020597, 2023). "Here, we investigated the direct involvement of MBTPS1 in colon cancer by integrating data from human CRC tumors and in vitro models of CRC-derived cell lines." (PMID 36300096, 2022). "The SREBP1/2 pathway was the only one that showed similar trends in the tumors and the MBTPS1 KO cells, results which are in agreement with earlier findings which showed that downregulation of SREBPs inhibits tumor growth in colon cancer." (PMID 36300096, 2022). "In conclusion, using a combined chemical and CRISPR/Cas9 –gene knockout approach we show that MBTPS1 plays a pivotal role in proliferation of colon cancer cells." (PMID 36300096, 2022). "Collectivity, genetic and pharmacological inhibition in colon cancer-derived HT-29 and HCT-116 cells indicate that MBTPS1 plays an essential role in proliferation of cells of this cancer type." (PMID 36300096, 2022). "To determine whether MBTPS1 is directly involved in proliferation of colon cancer cells, we treated two human-derived epithelial adenocarcinoma cells, HT-29 and HCT-116, with a MBTPS1 chemical inhibitor (PF-429242) and measured the effect on cell proliferation." (PMID 36300096, 2022).
Stroke (19 papers, 2013 to 2026). Sudden impairment of blood flow to a part of the brain due to occlusion or rupture of an artery to the brain. "A predictive model with 89.6% accuracy was identified using 6 network-central and differentially expressed genes (ID3, MBTPS1, NOG, SFXN2, BMX, SLC22A1), characterized by large differences in association network connectivity between stroke and control samples." (PMID 31391037, 2019). "In contrast, the connectivity of the other 5 genes is higher in the stroke vs. control networks: for MBTPS1, the control and stroke d = 1 neighborhoods have 20 vs. 49 genes, respectively, for NOG 13 vs. 65, for SFXN2 42 vs. 62, for BMX 22 vs. 61, and for SLC22A1, 15 vs. 63 neighbors." (PMID 31391037, 2019). "The mRNAs of ID3, MBTPS1, NOG, and SFXN2 have lower concentrations (are down-regulated) in the stroke samples (log FC = − 0.915, − 0.356, − 0.752, − 0.301, respectively) while BMX and SLC22A11 are up-regulated (log FC = 0.456, 0.365) in the stroke patients." (PMID 31391037, 2019). "Expression values from the genes ID3, MBTPS1, NOG, SFXN2, BMX, and SLC22A1 can jointly distinguish stroke from non-stroke samples with a high level of accuracy: 89.6% of samples are correctly classified in cross-validation sampling." (PMID 31391037, 2019).
colorectal cancer (11 papers, 2016 to 2025). A primary or metastatic malignant neoplasm that affects the colon or rectum. "Previous studies indicate that several of MBTPS1 downstream targets are implicated in growth of colorectal cancer (CRC) cells." (PMID 36300096, 2022). "By combining the information derived from the two datasets herein, we conclude that another PC, MBTPS1 plays a significant role in regulating proliferation of colorectal cancer cells." (PMID 36300096, 2022). "The goal of this study was to determine whether MBTPS1 may serve as a master regulator in proliferation of colorectal cancer (CRC)." (PMID 36300096, 2022). "The dataset obtained from patients with colorectal cancer provided valuable information regarding significant correlations between MBTPS1 expression and some, but not all, of its downstream targets." (PMID 36300096, 2022).
dyslipidemia (10 papers, 2009 to 2024). "In this study, three CpG sites in MBTPS1, two CpG sites in INSIG1, one CpG site in INSIG2, seven CpG sites in FBXW7, and six CpG sites in AMFR were found to be associated with dyslipidemia." (PMID 36570009, 2022).
spondyloepiphyseal dysplasia (4 papers, 2022 to 2024). An osteochondrodysplasia that results in abnormalities of bone growth in the vertebral column and the epiphysis. "The Kondo-Fu type of spondyloepiphyseal dysplasia (SEDKF) is a rare skeletal dysplasia caused by homozygous or compound heterozygous mutations in the MBTPS1 gene." (PMID 38337829, 2024). "Summary of the clinical and genetic features of spondyloepiphyseal dysplasia with MBTPS1 mutation reported in the literature vs. our proband." (PMID 36714646, 2022). "Notably, we report a Chinese rare case of spondyloepiphyseal dysplasia and validate its pathogenic synonymous variant in the MBTPS1 gene." (PMID 36714646, 2022).
alopecia (2 papers, 2022 to 2023). Hair loss usually from the scalp. "Another research introduced two unrelated and ethnically diverse children probands presented a new entity named cataract, alopecia, oral mucosal disorder, and psoriasis-like (CAOP) syndrome and WES and Sanger sequencing of both patients identified compound heterozygous variants in the MBTPS1 gene." (PMID 36714646, 2022).
familial hypercholesterolemia (2 papers, 2021 to 2022). An inheritable form of hyperlipidemia, in which there are excess lipids in the blood.
arenavirus infection (1 paper, 2012). "The relevance for SKI-1/S1P for productive arenavirus infection in vivo is further illustrated in mice homozygous for the hypomorphic Mbtps1 wrt allele (woodrat mutation), carrying a defective but still partially active SKI-1/S1P are resistant to LCMV infection." (PMID 23202458, 2012).
colorectal adenocarcinoma (1 paper, 2022). The most common type of colorectal carcinoma. "In order to test the hypothesis that MBTPS1 is directly involved in CRC proliferation, we first determined its expression in colorectal tumors in comparison to normal surrounding tissue from patients diagnosed with low or moderate colorectal adenocarcinoma." (PMID 36300096, 2022).
esophageal cancer (1 paper, 2025). A primary or metastatic malignant neoplasm involving the esophagus. "We observed a significantenrichment of PCSK6, PCSK9,MBTPS1, and FURIN mRNAs in the tumor tissue,which may be indication of the involvement of these PCs in the development andprogression of esophageal cancers." (PMID 40264581, 2025).
esophageal tumors (1 paper, 2025). "Our analysis revealed increased PCSK6,PCSK9, MBTPS1, and FURINexpressions in human esophageal tumors." (PMID 40264581, 2025).
Hypocholesterolemia (1 paper, 2012). An decreased concentration of cholesterol in the blood. "We demonstrate that a hypomorphic mutation of Mbtps1 called woodrat (wrt) caused hypocholesterolemia, as well as progressive hypopigmentation of the coat, that appears to be mechanistically unrelated." (PMID 22540041, 2012).
Pectus carinatum (1 paper, 2022). A deformity of the chest caused by overgrowth of the ribs and characterized by protrusion of the sternum. "These might explain the relationship between the mutated MBTPS1 with our patient's clinical features especially the skeletal dysplasia characterized by hyperextension of the palms, pectus carinatum scoliosis, multiple thoracolumbar vertebral bones dysplasia and severely decreased bone density." (PMID 36714646, 2022).
cancer (231 papers, 2006 to 2026). A tumor composed of atypical neoplastic, often pleomorphic cells that invade other tissues. "MBTPS1, which encodes the Membrane-Bound Transcription Factor Peptidase protein, has been implicated in the process of cancer cell proliferation." (PMID 40313868, 2025). "MBTPS1 belongs to the family of proprotein convertases (PCs), some of which have been implicated in cancer cell proliferation." (PMID 36300096, 2022). "The levels of another MBTPS1 target, BDNF, were also found to be elevated in human CRC samples where its presence was associated with reduced apoptosis of cancer cells." (PMID 36300096, 2022).
tumor (205 papers, 2006 to 2026). "The expression level of MBTPS1 mRNA in the tumor tissues of CRC patients is positively correlated with SREBPs." (PMID 37020597, 2023). "Given the positive correlation between the expression of MBTPS1 and the SREBP encoding genes, we next examined the transcript levels of downstream gene targets of SREBPs within the same tumor samples." (PMID 36300096, 2022). "In some patients, MBTPS1 expression was comparable between tumor samples and normal surrounding tissue (green dots)." (PMID 36300096, 2022). "In the remaining tumor samples, we found that MBTPS1 levels were either significantly decreased (light blue dots) or significantly increased (red dots)." (PMID 36300096, 2022). "Three categories of MBTPS1 expression were noticeable among the tumor samples." (PMID 36300096, 2022). "We found significantly increasedexpressions of the PCSK6, PCSK9,MBTPS1, and FURIN genes in tumor tissue,which may indicate the involvement of these PCs in the formation andprogression of esophageal malignancies." (PMID 40264581, 2025).
infection (52 papers, 2010 to 2025). The state of being infected such as from the introduction of a foreign agent such as serum, vaccine, antigenic substance or organism. "Among these, disruption of the canonical SREBP regulators SCAP, MBTPS1, and MBTPS2 conferred resistance to SARS-CoV-2 infection, with a similar effect for infection with the ACE2-independent HCoV-OC43 and HCoV-229E but not the ACE2-dependent HCoV2-NL63." (PMID 35231079, 2022).
skeletal dysplasia (3 papers, 2022 to 2024). Any Mendelian diseases that affects growth and development of the skeleton. "A patient reported with a recessive mutation in the MBTPS1 gene, encoding S1P, has features of a skeletal dysplasia, including growth retardation, kyphoscoliosis, and dysmorphic facial features, but intriguingly not OI." (PMID 39127989, 2024). "A novel autosomal recessive skeletal dysplasia resulting from pathogenic variants in membrane-bound transcription factor peptidase, site 1 (MBTPS1) has been recently delineated." (PMID 36714646, 2022).
MBTPS1 also shares sentences with these, for which no sentence is quoted: multiple sclerosis (45 papers); Obesity (33); Sepsis (32); asthma (22); Hypertension (21); COVID-19 (20); liver fibrosis (20); ovarian carcinoma (20); autoimmune disease (18); glioblastoma (18); lung carcinoma (18); pulmonary fibrosis (18); colitis (17); melanoma (16); rheumatoid arthritis (16); Cerebral ischemia (15); glioma (15); viral infection (15); cardiovascular diseases (14); lymphopenia (14); psoriasis (14); inflammatory bowel disease (13); myocardial infarction (13); neurodegenerative disease (13); ischemia (12); hepatocellular carcinoma (11); immune diseases (11); Insulin resistance (11); ischemic stroke (11); lung diseases (11).
A further 308 diseases each share a sentence with MBTPS1 in 10 papers or fewer.